MUC1 (mucin 1, cell surface associated)
Diseases named in the same sentence as MUC1 in open-access papers (continued):
Sharing a sentence is not in itself a finding about the gene and the disease.
breast carcinoma (continued). "With little information regarding MUC1 overexpression and the progression of canine mammary tumors, we tried to investigate the potential effect of overexpressed MUC1 in both in vitro and in vivo environments." (PMID 33375426, 2020). "MUC1 overexpression enhances tumor invasiveness and aggressiveness and promotes metastasis in breast cancers." (PMID 31470531, 2019). "Monoclonal antibody, TAB004, specifically recognizes the aberrantly glycosylated tumor form of MUC1 (tMUC1) in all subtypes of breast cancer including 95% of triple-negative breast cancer (TNBC) while sparing recognition of normal tissue MUC1." (PMID 31178870, 2019). "For solid tumors, a CAR specific for both HER2 and MUC1 had promising in vitro results in a breast cancer model, and a dual-target CAR specific for HER2 and IL13Rα2 showed greater success than single-target CARs in a xenograft glioma model." (PMID 30804938, 2019). "Another study demonstrated that co-administration of a MUC1 peptide vaccine with a mutant isoform of VEGF165b produced an enhanced immune response against breast cancer." (PMID 31693710, 2019). "Among these, mAb GGSK-1/30 was identified that specifically recognized the hu(TA)MUC1-glycopeptide pattern on human breast cancer cells whereas fully glycosylated huMUC1 expressed by healthy breast epithelial cells was not recognized." (PMID 31588183, 2019). "Preclinical evaluation of the newly developed HER2 hybrid peptide and MUC1 peptide for the detection of breast cancer is briefly presented here." (PMID 31470531, 2019). "In particular, Siglec-9 interacts with sialic acids on cancer cells (i.e., with MUC1, a high molecular weight glycoprotein expressed on adenocarcinoma cells including breast cancer) leading to immune suppression." (PMID 31430935, 2019). "In the present study, we performed in vitro and in vivo evaluation of HER2 and MUC1 derived peptides as potential candidates for breast cancer imaging." (PMID 31470531, 2019). "The autologous breast cancer cells all expressed high levels of MUC-1/HER-2 and variable levels of the epithelial (Ep-CAM) and epithelial progenitor (CD49f) markers as determined by flow cytometry." (PMID 30283982, 2019). "Promising results were obtained using this construct to treat MUC-1 overexpressing MCF-7 breast cancer cells." (PMID 31888119, 2019). "For example, MUC1 carrying the sialylated core 1 glycan (MUC1-ST) on breast cancer cells, was recently shown to bind to Siglec-9 on primary human monocytes and macrophages, inducing a secretome signature unique to each cell type." (PMID 31143186, 2019). "In another landmark study, chimeric antigen receptor (CAR)-T cell therapy targeting the tumor antigen MUC1 was shown to be effective against breast cancer in mouse models." (PMID 31366131, 2019). "In one recent study, a vaccine based on a MUC1 glycopeptide epitope conjugated to Tetanus Toxoid showed potent activity as a preventative vaccine against breast cancer." (PMID 31693710, 2019). "Vaccines based on human MUC1 have demonstrated particular efficacy in preclinical mouse models of breast cancer." (PMID 31693710, 2019). "Several molecules and receptors are involved in the interactions between cells, such as ICAM-1 expressed on MSC and mucin-1 (MUC-1) on the cell surface of breast cancer cells." (PMID 31547627, 2019). "IGF-1R up-regulates MUC1 expression in breast cancer cells in a PI3K/Akt signaling pathway-dependent manner and subsequently promotes epithelial-mesenchymal transition that is important in metastasis." (PMID 30041514, 2019). "A nanocomposite of aptamer−gold nanoparticle-hybridized graphene oxide (Apt-AuNP−GO) was designed as a photothermal treatment of MUC1-positive human breast cancer cells (MCF-7)." (PMID 31861277, 2019).
breast carcinoma (continued). "In the present study, we designed the CH-based nanocarrier for co-delivery of DTX and IGF-1R siRNA, and subsequently, MUC1 Apt was conjugated to the NPs for evaluating cell viability and genes expression in metastatic breast cancer cells." (PMID 30041514, 2019). "GGSK-1/30 is characterized by the fact that it exclusively recognizes a clearly defined synthetic MUC1-derived glycopeptide which was concomitantly demonstrated to block its binding to human breast cancer cells." (PMID 31588183, 2019). "MUC1 is expressed in over 90% of breast cancer, making MUC1 the most relevant and important antigen for breast cancer targeting." (PMID 31178870, 2019). "Specifically, we deployed these combinational treatment regimens in transgenic mice that express human MUC1 (MUC1.Tg mice), and which were orthotopically injected with a murine syngeneic breast cancer cell line expressing human MUC1 (MTag.MUC1 cells)." (PMID 31693710, 2019). "The specific immunohistochemical staining of breast cancer tissue with the mAb GGSK-1/30 confirmed that (TA)MUC1 represents a promising marker for diagnosis and most likely prognosis." (PMID 31588183, 2019). "A study of MUC1 in breast cancer cells suggested the existence of MUC1-containing sub-populations of lipid rafts which contribute to its secretion via exosomes." (PMID 31387973, 2019). "Vaccination of a group of stage II breast cancer patients with oxidized mannan-MUC1 resulted in significantly lower rates of recurrence and a longer time to recurrence compared to patients that had received placebo." (PMID 31693710, 2019). "Immunizations against hu(TA)MUC1 enabled us to generate a unique antibody that specifically recognizes hu(TA)MUC1 glycopeptides on breast cancer cells." (PMID 31588183, 2019). "In the present study, we generated a breast cancer cell line from the tumors of PyV MT mice, and overexpressed full length human MUC1." (PMID 31693710, 2019). "MUC1-aptamers have been used to targeted drug delivery to several types of cancers, including breast cancer cells." (PMID 31888119, 2019). "The soluble form of MUC1 is also known as CA15-3 antigen, and is the most widely used diagnostic and prognostic serum marker in breast cancer." (PMID 31514468, 2019). "Our experiments also altered the expression of MIR210HG, which in turn affects the expression of MUC1 protein, and ultimately regulates the EMT process associated with tumor metastasis in breast cancer." (PMID 31399552, 2019). "Both MIR210HG and MUC1 show significant expression levels in a variety of solid tumors, including invasive breast cancer tissue." (PMID 31399552, 2019). "The findings from these clinical trials suggest that MUC1-based vaccines should be tailored to particular subtypes and stages of breast cancer." (PMID 31693710, 2019). "It should be noted that MUC1 overexpression is not limited to breast cancer alone as it is highly expressed on the entire cell surface of a wide range of carcinomas including prostate, lung, gastrointestinal tract, and other epithelia." (PMID 31470531, 2019). "One possible explanation for the increase of MUC1 mRNA levels in breast carcinoma cells is activation of the single STAT-binding site of the MUC1 promoter by IFN-γ and fibrogenic IL-6." (PMID 31514468, 2019). "In a breast cancer model, the investigators engineered a MUC1 CAR that coexpressed a cytokine switch receptor (4/7ICR) with an IL-4 receptor extracellular domain fused to an IL-7 intracellular signaling domain." (PMID 30804938, 2019). "It is expected that the overexpression of MUC1 on breast cancer would facilitate target specific imaging and therapy using synthetic MUC1-derived peptide." (PMID 31470531, 2019). "The immune histochemical data which confirmed an exclusive binding of mAb GGSK-1/30 to (TA)MUC1-glycopeptides indicated that this mAb can be used for the diagnosis of breast cancer." (PMID 31588183, 2019).
breast carcinoma (continued). "Studies have also used CD28 with dual CARs, such as HER2/MUC1 bispecific CARs in in-vitro breast cancer models and HER2/IL13Rα2 CARs in xenograft glioma models." (PMID 30804938, 2019). "Lastly, to assess that MTag.MUC1 cells can form tumors, cells were injected orthotopically into the mammary fat pad of human MUC1.Tg mice, where they developed into mammary tumors." (PMID 31693710, 2019). "In conclusion, our findings indicate that indomethacin enhances the efficacy of the MUC1 peptide vaccine in treating MUC1-expressing mammary tumors." (PMID 31693710, 2019). "Studies based on mouse model have further established the roles of MUC1 in the initiation and invasiveness of breast cancer." (PMID 29423058, 2018). "We have previously demonstrated that MUC1 promotes EGFR-dependent breast cancer by inhibiting the degradation of EGFR and promoting its trafficking to the nucleus." (PMID 29464085, 2018). "To target breast cancer, we generated a retroviral vector encoding a first-generation human, codon-optimized CAR (1G) directed against the tumor-associated antigen MUC1." (PMID 29747685, 2018). "In another study, breast cancer cells were treated with HER2-mucin 1 (MUC1) CAR T cells which exhibited enhanced complementary signaling along with increased precise cytotoxicity against breast cancer cells expressing both antigens." (PMID 30108584, 2018). "Gene set analysis revealed that in human breast cancer cell lines the expression of these seven genes (MUC1, PLAU, FABP7, SPARC, HAS2, HAS3, SOX4) are higher in basal-B subtype compared to other subtypes." (PMID 29435170, 2018). "MUC1 is a mucin that is highly glycosylated with O-GalNAc glycans and is overexpressed and aberrantly glycosylated in greater than 90% of breast cancers." (PMID 29903935, 2018). "With regard to other cancer types, altered glycosylation of serum MUC1, a highly sialylated glycoprotein, exhibited potential for the early diagnosis of breast cancer and sialylation of serum MUC1 was also enhanced in colorectal cancer patients." (PMID 29680984, 2018). "In breast cancer GalNAcT6 can glycosylate and stabilise the MUC1 mucin, resulting in increased proliferation and decreased cell adhesion." (PMID 29903935, 2018). "In the randomized phase II Austrian Breast and Colorectal Cancer Study Group (ABCSG) 34 trial, the efficacy of a mucin-1 (MUC1) vaccination in combination with neoadjuvant treatment was tested in HER2-negative breast cancer patients." (PMID 30220928, 2018). "In the current study, we improved the potency of breast cancer-specific T cells by co-expressing an inverted cytokine receptor (ICR) on CAR T cells targeting MUC1." (PMID 29747685, 2018). "To confirm our finding, we chose 2 large breast cancer databases to analyze the expression of MUC1 and p50 in different subtypes." (PMID 29423058, 2018). "The expansion, persistence, potent anti-tumor activity, and safety profile exhibited by the second generation CAR.MUC1 and 4/7ICR modified T cells (2G.4/7ICR) support the clinical translation of this approach for the treatment of patients with breast cancer." (PMID 29747685, 2018). "Initially and aiming at the development of human anti-STn mAbs, phage display using novel naïve and immune human (derived from breast cancer patients) Fab phage display libraries were screened using biotinylated-STn peptides and MUC1 STn-IgG." (PMID 30111774, 2018). "The MUC1 promoter exhibits high transcriptional activity and can drive the expression of genes of interest in adenovirus or plasmid vectors for breast cancer targeted therapy." (PMID 29542355, 2018).
breast carcinoma (continued). "We focused on MUC1, which was shown to be particularly up-regulated (− 0.0000446-Padj) and has been demonstrated to be related to stemness in breast cancer and pancreatic cancer." (PMID 30518424, 2018). "To assess the potential involvement of MUC1-C in the regulation of BCL2A1, we established MDA-MB-468 breast cancer cells stably expressing tetracycline-inducible control shRNA (tet-CshRNA) or MUC1 shRNA (tet-MUC1shRNA)." (PMID 29760958, 2018). "We had previously demonstrated that MUC1 expression drives EGFR-dependent breast cancer (in the WAP-TGFα transgenic mouse model), including >60% reduction of EGFR-driven tumor formation in the absence of MUC1." (PMID 29464085, 2018). "Autoantibodies against other 2 autoantigens namely CMYC and MUC1 were selected as biomarkers for panel assay based on the performance of in-house developed ELISA in distinguishing canine mammary tumours from healthy controls." (PMID 30361548, 2018). "The multiplex assay, comprising a panel of candidate autoantigens (TPI, PGAM1, MNSOD, CMYC & MUC1) was used for screening circulating autoantibodies in 125 dog sera samples, including 75 mammary tumour sera and 50 healthy dog sera." (PMID 30361548, 2018). "There were significant differences in AUC of MUC1 and other autoantibody biomarkers (p < 0.05) indicating the usefulness of anti-MUC1 antibodies in detection of canine mammary tumour." (PMID 30361548, 2018). "The design of antigen specific vaccines can enlarge adaptive immune to a therapeutically beneficial level, for the levels of HER2 or MUC1 specific T-cells and antibodies are very low in most breast cancer patients." (PMID 28085094, 2017). "In keeping with the focus of the present work, we confirmed that MUC1 expression negatively correlates with that of BRCA1 in datasets from breast cancers and NSCLCs." (PMID 28785086, 2017). "We evaluated the use of TAB004, an antibody that recognizes the tumor form of the glycoprotein MUC1 (tMUC1), to aid early detection of breast cancer." (PMID 28680538, 2017). "It has also been suggested that the elevated level of antibody against CA15-3 (MUC-1) promotes the survival of patients with early stage ovarian, gastric, lung, pancreatic and breast cancers." (PMID 29285261, 2017). "In this drug delivery system, the aptamer serves for the targeted delivery to MUC1-positive breast cancer cells while the DNA tetrahedron is instrumental for the intercalation of DOX." (PMID 29144411, 2017). "We have recently described that luminal breast cancer cells widely express MUC1 and exhibit a low level of EGFR in situ, whereas triple-negative breast cancer cells are negative for MUC1 and positive for EGFR21." (PMID 28775276, 2017). "MUC-1 and syndecan-1 IHC staining of breast primary carcinoma tissues, performed in four patients (number 6, 9, 11, and 13), revealed strong brown staining of in situ and infiltrating breast carcinoma cells with both MUC-1 and syndecan-1 antibodies." (PMID 28399903, 2017). "Based upon these data, future trials evaluating the therapeutic effects of MUC1-derived vaccine in breast cancer are anticipated." (PMID 28085094, 2017). "Among the various mucins expression in breast cancer, MUC1 is reported as potential prognostic marker, having the strongest relationship with patient outcome and a potential target for therapeutic interventions in breast cancers." (PMID 28817726, 2017). "Breast cancer is immunogenic, and multiple putative tumor-associated antigens (TAAs), such as HER-2 and Mucin 1 (MUC1), are observed in the cancer." (PMID 28085094, 2017). "Collectively the present study identifies MUC1 as a novel therapeutic target for breast cancer, particularly for the subtype TNBC." (PMID 28464016, 2017). "The binding of VVA-B4 to primary cancer cells was attributed to the Tn-antigen-bearing MUC1 protein in primary breast cancer in relation to lymphatic metastasis." (PMID 28598369, 2017).
breast carcinoma (continued). "The observed absence of interactions observed between MGL and MUC1(ST), a structure expressed by breast carcinoma cells as well as by normal cells, points to the specificity of the MUC1(Tn) and MUC1(STn) MGL interaction." (PMID 28414807, 2017). "Its expression was reported to be increased at least 10-fold in several cancers such as adenocarcinoma, lung cancers, colon cancers and breast cancers, thus making MUC1 protein an attractive anti tumors target." (PMID 28841163, 2017). "We show here that both the MUC1 extracellular and intracellular domains contribute to EGF-induced EGFR activation in human colon and breast cancer cells with the predominate contribution from the MUC1 extracellular domain." (PMID 28731466, 2017). "MUC1 antibodies, CA 15-3 and CA 27-29, have been developed and used to detect recurrent breast cancer, monitoring the treatment of patients with advanced breast cancer and as a prognostic marker." (PMID 28680538, 2017). "Previously reported race and survival-associated genes including MUC1, GSTT2, PSPHL, SQLE, and TYMS were associated with race in this population-based study of women diagnosed with breast cancer." (PMID 29228969, 2017). "Given that MUC1 was specifically and significantly overexpressed in MT/Shc313F/313F breast cancer cells, we examined the relationship between MUC1 and STAT3 expression." (PMID 28276425, 2017). "MUC1 is overexpressed and aberrantly glycosylated in tumor cells, which contribute to the formation of epithelial cell carcinoma including breast cancer by promoting cell adhesion, blocking the apoptosis pathway and regulating intracellular growth signals." (PMID 28085094, 2017). "A strong syndecan-1 and MUC-1 expression was also documented by immunohistochemistry on primary breast cancer tissues, performed in four patients." (PMID 28399903, 2017). "While MUC1 transcriptional regulation by cytokines that signal via NF-κB factors in breast cancer cells is well documented, the role of NF-κB in regulating MUC1 gene expression in colon cancer cells has not been determined." (PMID 29285251, 2017). "In Yang’s work, DNA tetrahedron delivered doxorubicin into Mucin 1-positive breast cancer cells with the help of MUC1 aptamer." (PMID 28891335, 2017). "We have described clinicopathological characteristics of patients with breast cancer containing SRCs in relation to the expression levels of MUC1, MUC2, MUC4, MUC5AC, and MUC6." (PMID 27846863, 2016). "The mucin 1 (MUC1) transmembrane glycoprotein is aberrantly overexpressed in most breast cancers, including about 90% of TNBCs." (PMID 26930718, 2016). "All four of the peptides were equally good at stimulating lytic CD8+ T cells from the breast cancer patients against MCF-7 cells that express MUC1 endogenously." (PMID 27367740, 2016). "These peptides elicited CTLs from normal donors, as well as breast cancer patients, which were highly effective in killing MUC1-expressing MCF-7 breast cancer cells." (PMID 27367740, 2016). "GalNAc-T6 was reported to induce EMT-like changes by mediating MUC1 glycosylation in breast cancer, and promote EMT in prostate cancer cells treated by transforming growth factor-beta." (PMID 27276675, 2016). "Siglec-1 is also able to engage MUC1 from breast cancer cell lines in a sialic acid-dependent manner and Siglec-1+ macrophages are found in close contact with breast carcinoma cells." (PMID 27153100, 2016). "Studies in breast cancer cells have further supported epigenetic regulation of MUC1 promoter activation through histone modification and DNA methylation." (PMID 26930718, 2016). "In particular, the role of FRA-1 is well characterized in breast cancer, which also commonly exhibits MUC1 overexpression and consequent effects on signaling." (PMID 27220889, 2016). "Proteomic analysis has also demonstrated that the density of O-glycosylation is increased on MUC1 secreted from breast cancer cells." (PMID 27483328, 2016).